IL33 (interleukin 33)
Diseases named in the same sentence as IL33 in open-access papers (continued):
Sharing a sentence is not in itself a finding about the gene and the disease.
cognitive decline (11 papers, 2017 to 2025). "Future studies should assess the longitudinal changes of IL-33, Aβ, and tau in association with the cognitive decline." (PMID 32678011, 2020). "Recently, it has been reported that IL-33 can ameliorate AD-like pathology and cognitive decline, and the authors proposed that IL-33 is a promising potential treatment for AD." (PMID 29180837, 2017). "The cortex showed a reduced expression of Il33, a neuroimmune modulator, suggesting systemic vulnerabilities in cellular resilience that may contribute to cognitive decline." (PMID 40563967, 2025). "IL-33 was confirmed to ameliorate AD pathology and cognitive decline in APP/PS1 mice." (PMID 36186141, 2022). "An animal study showed that peripheral administration of IL-33 could reduce soluble Aβ levels and reverse cognitive decline in AD mouse models." (PMID 32678011, 2020). "IL-33 may be a neuroprotective factor at appropriate concentrations, while high concentrations of IL-33 in the neuropathological lesions of the brain may exacerbate neuroinflammation and cognitive decline." (PMID 35974336, 2022). "Taking these findings together, insufficient production of IL-33, rather than IL-33 depletion, might be associated with the risk of AD conversion and rapid cognitive decline." (PMID 32678011, 2020). "IL-33 administration increased the numbers of phagocytic microglial cells around APs, and the amounts of soluble Aβ were significantly reduced in the cortices of IL-33-treated APP/PS1 mice, preventing cognitive decline." (PMID 35974336, 2022). "IL-33 is one of the minor cytokines, most likely playing an anti-inflammatory role and preserving cognitive functions in non-AD patients, while AD patients have a lower level of IL-33 and cognitive decline." (PMID 35163247, 2022). "The aMCI and AD patients lacking IL-33 expression revealed significantly cognitive decline, while the patients with IL-33 expression preserved their cognitive function over 1-year period." (PMID 32678011, 2020).
cystic fibrosis (11 papers, 2015 to 2025). Autosomal recessive disorder caused by pathogenic variants in the CFTR gene (cystic fibrosis transmembrane conductance regulator), which encodes a chloride and bicarbonate channel expressed in epithelial cells, and follow the diagnosis criteria. "A follow-up study from the same group showed that Tpl2 also promoted IL-33 expression in response to Pseudomonas aeruginosa via the same pathway in airway epithelial cells expressing a Cystic Fibrosis mutation (CFTRdelF508)." (PMID 34691044, 2021). "Furthermore, varying degrees of IL-33 upregulation have been identified in patients with cystic fibrosis and silicosis, indicating a potential role for IL-33 in the pathogenesis of these diseases, necessitating further investigation in the future." (PMID 39301028, 2024). "In cystic fibrosis IL-33 has been shown to synergize with chemoattractants to promote neutrophil recruitment that might be more harmful than beneficial, like in CRSsNP." (PMID 28127565, 2016). "Interesting data on the role of HMGB1 and IL-33 have also emerged in the context of different respiratory diseases, such as disorders derived from respiratory syncytial virus (RSV) infection and cystic fibrosis." (PMID 36675299, 2023). "We found that, in CF AECs expressing a deletion of a phenylalanine at position 508 of the gene coding for Cystic Fibrosis Transmembrane Conductance Regulator (CFTRdelF508), exposure to live Pseudomonas aeruginosa upregulates IL-33 via the TLR2 and TLR5 signaling pathways." (PMID 26793709, 2015).
eosinophilic esophagitis (11 papers, 2016 to 2026). Eosinophilic esophagitis (EoE) is a chronic, allergic disease of the esophagus characterized clinically by symptoms of esophageal dysfunction (including vomiting, dysphagia, feeding disorders, food impaction and abdominal pain) which persist after treatment with proton pump inhibitors (PPIs). "IL‐33 induces activation of mouse basophils through their own ST2 receptor in epicutaneous sensitisation‐induced experimental eosinophilic esophagitis." (PMID 39654685, 2024). "Interestingly, the correlation between eosinophil‐mediated diseases and IL‐33/TGFβ co‐priming was also observed in one validation set involving eosinophilic esophagitis MCs." (PMID 40926620, 2025). "Moreover, we set out to validate our data in co-cultures of PBMC with human primary esophageal epithelial cells and in a novel inducible mouse model of eosinophilic esophagitis, characterized by extensive IL-33 secretion in the esophagus." (PMID 38318168, 2024). "Considerable scientific evidence confirms that interleukin (IL)-33 and its main receptor, suppression of tumorigenicity 2 (ST2), form a functional axis to modulate the development of esophageal inflammatory disorders, such as eosinophilic esophagitis and gastroesophageal reflux disease." (PMID 40520454, 2025).
glioblastoma (11 papers, 2017 to 2025). The most malignant astrocytic tumor (WHO grade IV). "Furthermore, while there is no differential IL-33 protein expression by tumor grade, elevated levels of IL-33 protein, and mRNA are associated with inferior survival in patients with recurrent glioblastomas." (PMID 30515150, 2018). "In addition, IL-33 expression is associated with poor survival in glioblastoma patients." (PMID 34503065, 2021). "Glioblastoma also affects the expression of inflammatory proteins such as C-X-C motif chemokine 9 and Interleukin-33, providing new insights into the mechanisms of glioblastoma genesis and clinical research." (PMID 38784036, 2024). "Transcriptomic analysis showed that FGF21 expression was inversely associated with the risk of developing glioblastoma, whereas an increased risk was linked to elevated levels of CXCL9 and IL-33." (PMID 38784036, 2024). "Collectively, these findings suggest that FGF21 expression is inversely associated with the risk of developing glioblastoma, whereas an increased risk is linked to elevated levels of CXCL9 and IL-33." (PMID 38784036, 2024). "IL-33 secreted by glioblastoma cells is involved in TAM recruitment and polarization towards pro-tumorigenic M2-like TAMs." (PMID 34503065, 2021). "Herein we identify the dual function cytokine IL-33 as an orchestrator of the glioblastoma microenvironment that contributes to tumorigenesis." (PMID 33020472, 2020). "We analyzed the mRNA expression data from TCGA database and found the expression of IL-33 was significantly increased in glioblastoma tissues compared with normal brain." (PMID 32003751, 2020). "We also observed elevated IL-33 expression in the cancer stem cell cluster when compared to other (non-stem cell) microdissected anatomical structures from the Ivy Glioblastoma Atlas Project." (PMID 33020472, 2020). "Using the IVW method, we discovered a possible correlation between an increased risk of glioblastoma and elevated levels of C-X-C motif chemokine 9 (CXCL9) and Interleukin-33 (IL-33) (OR, 1.03; 95% CI: 1.01, 1.06; p = 0.021; OR, 1.03; 95% CI: 1.03, 1.06; p = 0.030)." (PMID 38784036, 2024). "To investigate the role of Cystatin D, FGF21, IL-33 and CXCL9 in glioblastoma, we analyzed the correlation between the expression of these genes and survival prognosis characteristics in patients with glioblastoma." (PMID 38784036, 2024). "Additionally, increased FGF21 expression positively correlated with improved overall survival (OS), whereas increased levels of CXCL9 and IL-33 were associated with decreased OS in patients with glioblastoma, although the difference was not statistically significant." (PMID 38784036, 2024). "Reverse MR and transcriptomic analyses in this study also revealed a potential correlation between glioblastoma, CXCL9, and IL-33." (PMID 38784036, 2024). "The results demonstrated a significant downregulation of FGF21 expression in glioblastoma tissues, whereas both CXCL9 and IL-33 were notably upregulated." (PMID 38784036, 2024). "As has been described previously demonstrating no nuclear staining of IL-33 in normal brain tissues but strong nuclear staining in glioblastoma by Gramatzki." (PMID 32003751, 2020). "Moreover, our reverse MR analysis revealed that glioblastoma may contribute to increased concentrations of C-X-C motif chemokine 9 (CXCL9) and Interleukin-33 (IL-33) in the bloodstream." (PMID 38784036, 2024).
graft versus host disease (11 papers, 2017 to 2022). An immune system disorder that occurs after allogeneic hematopoietic stem cell transplant and is a reaction of donor immune cells against host tissues. "In addition to these, IL-33/ST2 axis has been found close related to graft-versus-host disease (GVHD)." (PMID 34950738, 2021). "Under autoimmune, inflammatory and tissue injured circumstances, such as experimental autoimmune encephalomyelitis, graft versus host disease (GVHD), sepsis, and acute lung injury, IL-33/ST2 axis increases Treg cells numbers and enhances its protective function." (PMID 32908451, 2020). "Regarding graft versus host disease (GVHD), ST2+ Tregs ameliorate the intestinal damage through an IL-33 dependent increase of a KLRG1+ subpopulation." (PMID 35572605, 2022).
ileitis (11 papers, 2012 to 2024). "In this regard, host alarmins S100A11 and IL-33 have been implicated in monocyte recruitment and aggravated ileitis respectively during T. gondii infection, although their role in IL-12-driven immunity is not clear." (PMID 34597344, 2021). "IL-33 also drives eosinophil infiltration and pathogenic type 2 helper T cell immune responses leading to chronic experimental ileitis." (PMID 32410845, 2020). "Other factors that were only increased in the BALF of SHIP-1−/− mice with ileitis were IL-33 and TNFα, while IL-6, CCL2, and CCL4 were more significantly increased in the lungs of SHIP-1−/− mice with ileitis." (PMID 39432107, 2024). "Blockage of the IL-33/ST2 pathway lessens the severity of ileitis in mice induced by oral T. gondii, illustrating the organ-dependent response of IL-33." (PMID 37375100, 2023). "Meanwhile, in the SAMP1/YitFc spontaneous ileitis model, IL-33 was also involved in increased pro-fibrogenic Th2 response." (PMID 37691056, 2023). "In this study, the IL-33/ST2 pathway promoted NOD2-induced ILC2 expansion in ileitis; furthermore, blocking IL-33 protected SAMP mice." (PMID 34581755, 2021). "Oral T. gondii infection (30 cysts of 76K strain) induces acute lethal ileitis in sensitive C57BL/6 (B6) mice with increased expression of IL-33 and its receptor ST2 in the ileum." (PMID 31057534, 2019). "Both ST2 and IL-33 are upregulated in the intestine and IL-33R/ST2 deficient mice have attenuated ileitis with increased IL-22 expression." (PMID 31057534, 2019). "Investigation is further warranted to study the role of IL-33 during the early, acute phase of SAMP ileitis, as well as the specific role of epithelial-derived IL-33 and IL-33's direct effects on the intestinal epithelium." (PMID 23062310, 2012). "IL-33 levels are reduced in NOD2 deficient mice, resulting in lower levels of ILC2 and acerbated inflammatory disease, indicative of a pathogenic role of the IL-33/ILC2 axis in the early stages of ileitis." (PMID 36189323, 2022). "Therefore, the data strongly suggests that IL-33 signaling via IL-33R/ST2 is critical for the inflammatory response in T. gondii induced ileitis." (PMID 31057534, 2019). "Therefore, IL-33 appears to be critical for the control of T. gondii induced ileitis and we asked whether other inflammatory cytokine are involved." (PMID 31057534, 2019). "However, the role of IL-33 or IL-33R/ST2 upon T. gondii induced ileitis is unknown." (PMID 31057534, 2019). "Here we show that IL-33 is involved in ileitis, since absence of IL-33R/ST2 attenuated neutrophilic inflammation and Th1 cytokines upon T. gondii infection with enhanced survival." (PMID 31057534, 2019). "Previous work demonstrated that neuroinflammation induced by T. gondii is IL-33-dependent, since IL-33R/ST2 deficient mice have increased parasite growth and severe cerebral toxoplasmosis, but the ileitis was not investigated." (PMID 31057534, 2019).
nematode infection (11 papers, 2013 to 2025). "Regulatory T cells can also bind IL-33; therefore, this molecule can increase or decrease resistance to nematode infection." (PMID 40565065, 2025). "The production of IL-4 and IL-13 during nematode infection in vivo is mainly initiated by the alarmins IL-25, IL-33 and TSLP released by epithelial and stromal cells." (PMID 38414039, 2024). "First, we used a dose of IL-33 capable of inducing the same ILC2 level as that induced by nematode infection, which is lower than the dose used in the prior work." (PMID 30283458, 2018). "In the lung, type II alveolar epithelial cells possess IL-33 even in the normal state and increase its expression by nematodes infection." (PMID 30283458, 2018). "At day 21, when the number of nematode infection-induced ILC2s reached their population peak, the number of IL-33-induced ILC2s decreased." (PMID 30283458, 2018). "Our studies using administration of recombinant cytokine, a fungal allergen and nematode infection are consistent with these studies and demonstrate that IL‐33‐dependent alternative activation is also reliant on IL‐4Rα in the serous cavities." (PMID 27592711, 2016). "In some senses, IL-25 mirrors many of the effects of IL-33 in studies of immunity to GI nematode infection." (PMID 24942690, 2014). "Both IL-25 and IL-33 are upregulated during nematode infection and play an important role in host protective immunity." (PMID 23536877, 2013). "IL-33 is particularly important for resistance to nematode infection." (PMID 40565065, 2025). "We hypothesise that HpBARI inhibits the initiation of type two immune responses during damage-induced IL-33 release in nematode infection." (PMID 32420871, 2020). "IL-33 has received particular attention as an alarmin and can be released from damaged epithelial cells 79 and is, therefore, well placed to initiate rapid changes following GI nematode infection." (PMID 24942690, 2014). "It remains to be determined whether macrophages can produce type 2 cytokines during nematode infection or in response to IL-25/IL-33." (PMID 23536877, 2013). "Nevertheless, when we infected IL-33-treated mice with N. brasiliensis, we did not observe the resistance to subsequent nematode infection and increases in pulmonary ILC2s and eosinophils that occurred in Sv-exp mice." (PMID 30283458, 2018). "Current data would suggest, however, that a critical role for IL-33 may not apply to all GI nematode infections." (PMID 24942690, 2014). "It is of note that in other immune conditions, subsets of FoxP3+ Tregs have been identified such as the IL-33 driven ST2+ FoxP3+ Tregs that prolong transplant graft survival 143, and it may be that similar populations require examination in the context of GI nematode infection." (PMID 24942690, 2014). "A lack of IL-33 severely impaired the accumulation of ILC2s and eosinophils along with the induction of cytokine mRNA expression in Sv-exp mice, indicating that IL-33 is required for the accumulation of ILC2s and the severe lung inflammation in sequential nematode infection." (PMID 30283458, 2018).
osteoarthritis (11 papers, 2013 to 2024). A noninflammatory degenerative joint disease occurring chiefly in older persons, characterized by degeneration of the articular cartilage, hypertrophy of bone at the margins and changes in the synovial membrane. "The results of this study will support the notion that targeting inflammation by blocking IL-33 and increasing IL-37 in osteoarthritis will attenuate cartilage loss." (PMID 35565085, 2022). "Thus, vitamin D supplementation in patients with a vitamin D deficiency may be beneficial in treating patients with osteoarthritis and may be a novel therapeutic strategy by blocking the effect of IL-33." (PMID 34842603, 2021). "The articles were searched as follows: “HMGB1” AND “osteoarthritis”; “S100 b protein human” AND “osteoarthritis”; “Interleukin-33” AND “osteoarthritis”." (PMID 37569519, 2023). "Synovial fluid samples from septic arthritis and osteoarthritis individuals were assessed regarding IL-33 and soluble (s) ST2 levels." (PMID 29867945, 2018). "First, the IL-33 and sST2 levels in the synovial fluid of patients with septic arthritis and osteoarthritis were determined." (PMID 29867945, 2018). "These clinical results indicate that there are higher levels of IL-33 in septic arthritis primary foci than in osteoarthritis." (PMID 29867945, 2018). "Here, we found that IL-33 was abundantly increased in chondrocytes of osteoarthritis, especially the chondrocytes of weight-bearing cartilage." (PMID 29095435, 2017). "The IL-33 levels in samples from synovial fluid were significantly increased, whereas no sST2 levels were detected in patients with septic arthritis when compared with osteoarthritis individuals." (PMID 29867945, 2018). "In our previous study, we demonstrated that IL-33 serum concentration was significantly higher in patients with RA than in age-matched healthy controls, patients with primary Sjogren’s syndrome, and patients with osteoarthritis." (PMID 23967327, 2013). "Furthermore, decreased proteoglycan loss in human OA cartilage with IL-37 via inhibition of MMP-3 expression and the protection of stem cells in an inflammatory osteoarthritis-like microenvironment for cartilage formation support IL-33 and IL-37 as potential therapeutics." (PMID 34842603, 2021). "In conclusion, inhibiting IL-33 can significantly lower inflammatory factor levels in the knee joint, including IL-33 and MMP-9, and it can improve cartilage breakdown in osteoarthritis of the knee." (PMID 39172956, 2024). "In this study, we found that expression of IL‐33 and ST2 is increased in human and murine osteoarthritis (OA) samples." (PMID 33133598, 2020). "The cytokine IL‐33 and its receptor ST2 have been shown to play a role in immune and inflammatory diseases, but their role in osteoarthritis is unknown." (PMID 33133598, 2020). "We observed that patients have significantly more IL-33 and no detectable concentrations of sST2 in their synovial fluid compared those of the osteoarthritis patients." (PMID 29867945, 2018). "Taken together, the results of this study suggest that modulating expression of IL-33, IL-6, TNF-α, TLRs, DAMPs, and MMPs with vitamin D supplementation may serve as a novel therapeutic to attenuate inflammation and cartilage degeneration in osteoarthritis." (PMID 34842603, 2021).